TRIM44 (tripartite motif containing 44)
Diseases named in the same sentence as TRIM44 in open-access papers (continued):
Sharing a sentence is not in itself a finding about the gene and the disease.
cancer (continued). "Interestingly, we showed that CDK19 is upregulated by TRIM44 siRNAs in a pluripotent human testicular embryonic cancer cell line, suggesting that TRIM44 also plays a tumor-promoting role in the pathogenesis of other types of cancer by modulating CDK19 expression." (PMID 28885545, 2017). "Overexpression of TRIM44 and downregulation of Hippo-YAP1/TAZ can reduce E-cadherin and inhibit the malignant behavior of cancer cells, such as proliferation." (PMID 40061926, 2025). "TRIM44, a known tumor-suppressing gene, downregulates Fyn-related kinase (FRK) and promotes cancer progression in renal cell carcinoma." (PMID 40723250, 2025). "‘Metabolic pathways’ include UDP-glucose 6-dehydrogenase (UGDH), tripartite motif containing 44 (TRIM44), and branched-chain amino acid transaminase 1 (BCAT1), and these genes are known to affect cancer development." (PMID 37667226, 2023). "TRIM44 and TRIM59, identified as oncogenes, are enriched in cancers and involved ininvasion stimulus, which predicts poor prognosis." (PMID 34284744, 2021). "However, the precise functions of TRIM44 in cancer remain unclear." (PMID 30089913, 2019). "In recent years, many research studies have shown that TRIM family proteins, such as TRIM3, TRIM11, TRIM19, TRIM31, TRIM44 and TRIM59 have been demonstrated to serve a significant role in the tumorigenesis and progression of numerous cancer types." (PMID 30484263, 2019). "We found that TRIM44 expression was upregulated in ICC tissues compared with corresponding paratumorous tissues, which were consistent with the results from the public cancer database." (PMID 29446253, 2018). "Also, miR-34a-5p suppresses the signaling pathways that are key regulators in metabolic function related to the growth of cancer including Hippo-YAP1/TAZ, TRIM44, and FLSs-RA." (PMID 40061926, 2025). "Interestingly, further studies have shown that TRIM44 activates the AKT/mTOR signal pathway, the FOXM1–EZH2 signaling pathway, and extracellular matrix remodeling in cancer progression, DNA damage repair, and autophagy." (PMID 39757165, 2025). "Most TRIM proteins, such as TRIM44 and TRIM59, exhibit a cancer-promoting role, consistently upregulated across several cancer types, whereas TRIM proteins like TRIM16 suppress cell proliferation and metastasis in neuroblastoma, melanoma, ovarian cancer and breast cancer." (PMID 39451518, 2024). "TRIM44, a member of the TRIM protein family, is an efficient regulator of carcinogenesis and its overexpression is characteristic of facilitated cell proliferation and cancer metastasis." (PMID 33679655, 2021). "And when combined with all tumor data from the GEPIA database, the pooled results showed that cancer patients with a high level of TRIM44 tend to have a poor DFS, although there was no statistical difference." (PMID 32503466, 2020). "When combined with all data from 33 different types of malignant tumors in GEPIA, the Kaplan-Meier analysis suggested that cancer patients with a high expression level of TRIM44 exhibited poorer OS, compared with cases expressing a low level of TRIM44." (PMID 32503466, 2020). "This study not only reveals the pathological role of TRIM44 in NSCLC, but also suggests that it could be used as a prognostic factor and therapeutic target in NSCLC and, possibly, other cancers as well." (PMID 27058415, 2016). "The results of the combined analysis showed that over-expression of TRIM44 protein was significantly correlated with shorter overall survival (OS) (HR = 1.94, 95% CI: 1.60–2.35) and worse disease-free survival (DFS) (HR = 2.13, 95% CI: 1.24–3.65) in cancer patients." (PMID 32503466, 2020). "Preliminary functional studies show that siRNA knockdown of TRIM44 suppresses cancer cell migration and invasion; however, it is not known whether TRIM44 can induce tumor EMT." (PMID 27058415, 2016).
tumor (29 papers, 2016 to 2025). "Gain- and loss-of-function experiments in cell lines and mouse xenograft models were performed to elucidate the function and underlying mechanisms of TRIM44 induced tumor progression." (PMID 30922374, 2019). "Univariate analysis showed that AFP, tumor number, lymphatic metastasis, tumor size, embolus as well as TRIM44 staining were associated with OS and cumulative recurrence." (PMID 29446253, 2018). "Clinically, TRIM44 expression was positively associated with large tumor size (P = 0.035), lymphatic metastasis (P = 0.008) and poor tumor differentiation (P = 0.036)." (PMID 29446253, 2018). "In this study, we analyzed the association between TRIM44 expression and the pT classification in 50 samples with a tumor invasion front." (PMID 27058415, 2016). "Here, we identified TRIM44 as a tumor suppressor in ccRCC through integrated clinical and functional analyses." (PMID 40967439, 2025). "The result showed that TRIM44 was markedly upregulated in the tumor tissues compared with paired adjacent normal tissues (SH)." (PMID 41357604, 2025). "Mechanistically, ELDR functions as a competitive endogenous RNA (ceRNA) by sequestering tumor-suppressive miR-1343-3p in the cytoplasm, which consequently leads to the upregulation of the oncogene TRIM44." (PMID 41357604, 2025). "Several investigators found that Trim44 facilitated tumor development through activation of the AKT/mTOR signaling pathway, including phosphorylated P70S6K in several cases." (PMID 35855640, 2023). "Of note, a significant correlation was also found between the increased circNFIX and TRIM44 levels in tumor tissue samples from the OC patients and tumor size and FIGO stage." (PMID 38132461, 2023). "circNFIX and TRIM44 correlate with the tumor stage as defined by the International Federation of Gynecology and Obstetrics (FIGO) and with the size of ovarian tumors." (PMID 37514090, 2023). "Several investigations found that TRIM44 facilitates tumor development through activation of the AKT/mTOR signaling pathway, including phosphorylated P70S6K (also known as RPS6KB1) in several cases." (PMID 35855640, 2023). "Compared with nude mice injected with Ctrl cells, nude mice injected with TRIM44 cells had an increased tumor burden, suggesting that TRIM44 enhanced cisplatin resistance." (PMID 35541909, 2022). "At the same time, we also detected a significant increase in the expression of miR-194-5p and a significant decrease in the protein expression of TRIM44 in tumor tissues of sh-circ_0030018 group." (PMID 34150336, 2021). "TRIM44 was involved in the malignant biological behavior of tumor cells and played an intersection role in the gene regulatory pathways." (PMID 32503466, 2020). "We found that TRIM44 is involved in the malignant biological behavior of tumor cells and it plays an intersection role in the gene regulatory pathways." (PMID 32503466, 2020). "This study was designed to systematically assess the prognostic value of TRIM44 in human malignancies and summarize its possible tumor-related mechanisms." (PMID 32503466, 2020). "TRIM44 induced cell proliferation in vitro and tumor growth in vivo by accelerating the G1/S transition via the upregulation of cyclins and CDKs." (PMID 32503466, 2020). "Then, the tumours were examined by H&E and immunohistochemical staining to determine TRIM44 protein expression; the miR-192-5p mimic group demonstrated obviously lower expression." (PMID 31873114, 2019). "TRIM44 has been reported to be upregulated in many types of tumours, and TRIM44 is involved in tumour formation and progression." (PMID 31873114, 2019). "There is growing evidence that tripartite motif-containing protein 44 (TRIM44) plays crucial role in tumor development." (PMID 30922374, 2019). "In the present study, we found that the expression of TRIM44 was significantly higher in tumor tissues than in normal cervical tissues by both Western blotting and RT-PCR analysis." (PMID 30792262, 2019).
tumor (continued). "Multiple pathways are involved in TRIM44-induced tumor progression, including AKT, ERK1/2, and NF-κB signaling." (PMID 30922374, 2019). "Histochemically, the positive staining of TRIM44 mainly localized in the cell cytoplasm, and the intensity of TRIM44 in tumor cells is higher than that in peritumor cells." (PMID 29446253, 2018). "Western bolting indicated that the expression of TRIM44 was remarkably higher in ICC than that in adjacent tumor tissues (3.370 ± 2.314 vs. 1.249 ± 1.118, P = 0.0156)." (PMID 29446253, 2018). "We found that expression of TRIM44 was highly relevant with large tumor size, metastasis, poor tumor differentiation, and negatively related to patients' OS and recurrence." (PMID 29446253, 2018). "Multivariate analysis for 4 factors including tumor size, ER status, nuclear grade and TRIM44 IR showed that all of them are independent prognostic factors." (PMID 28885545, 2017). "Here, we report that the expression of TRIM44 was significantly increased in tumor tissues from patients with NSCLC." (PMID 27058415, 2016). "IHC analysis revealed that TRIM44 was clearly localized to the cytoplasmic compartment of tumor cells." (PMID 27058415, 2016). "Expression of TRIM44 mRNA was then examined in tumor and normal tissues using real-time quantitative RT-PCR." (PMID 27058415, 2016). "Expression of TRIM44 protein was significantly higher in tumor tissues than in adjacent normal lung tissues." (PMID 27058415, 2016). "We next examined TRIM44 protein expression in fresh tumor and normal tissues by western blot analysis." (PMID 27058415, 2016). "The results showed that the mean relative expression of TRIM44 mRNA in tumor tissues was significantly higher than that in normal lung tissues; indeed, tumor tissues expressed ~4.8-fold more TRIM44 mRNA than normal tissues (P = 0.003)." (PMID 27058415, 2016). "Clinically, TRIM44 expression was significantly downregulated in ccRCC tissues compared with adjacent normal tissues, and its reduced expression correlated with advanced tumor stage and poor patient prognosis." (PMID 40967439, 2025). "Furthermore, in nude mice with a GBM xenograft, systemic administration of a miR-623 mimic inhibited tumor development and suppressed expression of TRIM44 protein." (PMID 35071748, 2022). "Further, we have discussed the possible role of TRIM44 in tumor progression." (PMID 32503466, 2020). "However, for patients with CHOL or KIRC, a high level of TRIM44 mRNA in tumor samples indicated favorable OS in these cases." (PMID 32503466, 2020). "In addition, knockdown of TRIM44 inhibited the proliferation, migration, and invasion of tumor cells." (PMID 30792262, 2019). "In addition, higher TRIM44 expression was related to CC featuring lower tumor differentiation and an advanced stage." (PMID 30792262, 2019). "All these studies suggest that TRIM44 plays a considerable role in tumor development." (PMID 30792262, 2019). "Finally, western blot analyses of tumour tissues showed that miR-192-5p decreased TRIM44 protein expression." (PMID 31873114, 2019). "Furthermore, we found that TRIM44 expression was positively related to large tumor size (P = 0.035), lymphatic metastasis (P = 0.008), and poor tumor differentiation (P = 0.036)." (PMID 29446253, 2018). "Together with increasing production of MMP1 and enhancing motility, TRIM44 may promote tumor invasion and metastasis." (PMID 28885545, 2017). "To investigate whether TRIM44 silencing reduces tumor growth in vivo, we established stable A549/control and A549/shTRIM44 clones with more than 80% efficiency." (PMID 27058415, 2016). "Additionally, we examined lymphatic metastasis foci and matched primary tumor lesions from 30 NSCLC patients showing high expression of TRIM44." (PMID 27058415, 2016). "Additionally, TRIM44 induced cell proliferation in vitro and tumor growth in vivo by accelerating G1/S transition via upregulation of cyclins and CDKs." (PMID 27058415, 2016).
tumor (continued). "Therefore, we decided to analyze the effects of TRIM44 during specific phases of the cell cycle and examine its contribution to tumor cell proliferation." (PMID 27058415, 2016). "Thus, TRIM44 appears to be a vital promoter in tumor development." (PMID 29446253, 2018). "TRIM44 directly binds to LOXL2 and regulates its stability to remodel the tumor extracellular matrix and influence tumor immunity." (PMID 40936722, 2025). "Intriguingly, when compared to group III, group IV exhibited a significantly reduced tumor burden, indicating that BRCA1 is required for TRIM44-induced cisplatin resistance in vivo." (PMID 35541909, 2022). "Consistently, the protein levels of TRIM44, p-STAT3, BCL2, MMP9, HIF-1α and PIM1 were all decreased in SPATS2 knockdown tumor tissues, which underpinned the contribution of SPATS2-TRIM44-p-STAT3 axis to tumorigenic events in HCC." (PMID 33391405, 2021). "TRIM44 stabilizes HIF-1α via deubiquitination, which is a key transcription factor that regulates MM tumor growth, angiogenesis, and bone destruction." (PMID 30089913, 2019). "TRIM44 overexpression promotes the EMT program and, thus, tumor invasion/metastasis in NSCLC cells via the mTOR signaling pathway." (PMID 27058415, 2016). "The peripheral levels of TRIM44, CTSZ, CD164, and TIMP1 can stimulate granulocyte production in mouse bone marrow, and high levels of TIMP1 are positively correlated with increased immune infiltration levels of tumor-infiltrating lymphocytes." (PMID 40524208, 2025). "To examine whether a high level of TRIM44 influence tumor invasive and metastasis by MAPK pathway, we treated RBE‐TRIM44 with AZD6244, a MEK inhibitor (5 μmol/L, 24 h)." (PMID 29446253, 2018). "Co-IP assays and mass spectrometric analyses indicated that TRIM44 overexpression induces cell EMT through activating AKT/mTOR pathway via directly binding and stabilizing TOLL-like receptor 4 (TLR4), and TLR4 interference impeded TRIM44 induced tumor progression." (PMID 30922374, 2019). "Likewise, these markers were also confirmed by immunohistochemical staining in serial sections of ICC tissues, and in the positive TRIM44 staining of ICC tissues, downregulaton of E‐cadherin and up‐regulation of vimentin, β‐catenin and snail were observed in invasive tumor fringe and vice versa." (PMID 29446253, 2018).
infection (5 papers, 2012 to 2024). The state of being infected such as from the introduction of a foreign agent such as serum, vaccine, antigenic substance or organism. "TRIM44 was also observed to be expressed progressively with RV infection, although maximally expressed at 12 hpi when prominent infection was observed." (PMID 33679655, 2021). "The mRNA level of TRIM44 was upregulated upon infection with GDSH-01 and HEP-Flury strains, and the mRNA level of TRIM56 was elevated upon infection with GDSH-01 and HEP-Flury strains." (PMID 38731834, 2024). "In the light of our results, we infer that TRIM44 and CCNE1 are significant in triggering the EMT pathway during RV infection, a phenomenon that may be required for cell-to-cell spread of RV to expand its infection within the host." (PMID 33679655, 2021).
TRIM44 also shares sentences with these, for which no sentence is quoted: endometrial cancer (7 papers); neurodegenerative disease (3); osteosarcoma (2); adenocarcinoma (1); Cerebral ischemia (1); Endometrial adenocarcinoma (1); esophageal squamous cell carcinoma (1); head and neck squamous cell carcinoma (1); heart diseases (1); hypertrophic cardiomyopathy (1); hypertrophy (1); immune deficiency (1); invasive breast carcinoma (1); invasive ductal breast carcinoma (1); monoclonal gammopathy of undetermined significance (1); Myocardial fibrosis (1); oral cancer (1); pancreatic tumor (1).